EPHA3 (EPH receptor A3)
Diseases named in the same sentence as EPHA3 in open-access papers (continued):
Sharing a sentence is not in itself a finding about the gene and the disease.
tumor (continued). "Furthermore, treatment of mice with an antibody against EphA3 was sufficient to disrupt the stroma and vasculature and inhibit tumour growth." (PMID 37760615, 2023). "Bone marrow-derived MSCs from these mice also showed significantly attenuated stem cell-like capacity, as measured by survival and reproduction in colony forming assays, consistent with the known roles of Ephs including EphA3 in supporting less differentiated, stem cell-like cells in tumours." (PMID 37760615, 2023). "Tumour cell differentiation and apoptosis were seen following EphA3 knockdown in vivo." (PMID 36830852, 2023). "Here, we have developed novel transgenic mice in which EphA3 expression can be specifically and temporally suppressed by shRNA interference in adult mice prior to tumour inoculation, thus avoiding the developmental and possible compensatory effects of germline gene knockout." (PMID 37760615, 2023). "Indeed, MSCs are known to enhance tumour angiogenesis in response to hypoxic signalling, in a process analogous to wound-healing, and EphA3 is up-regulated by hypoxia, including during neo-angiogenesis." (PMID 37760615, 2023). "Notably, tumours in mice with doxycycline-induced EphA3 knockdown were significantly smaller/delayed, suggesting a functional role for EphA3 in MSCs/CAFs that promote tumour growth." (PMID 37760615, 2023). "In particular, EphA2, EphA3, EphA4, and EphB4 are promising therapeutic candidates, based on increased expression in tumours and the TME, and drugs targeting these receptors have shown some promise in tumour models, with mixed success in the limited clinical studies performed to date." (PMID 36830852, 2023). "We also showed that treatment of EphA3+ MSCs with the agonistic EphA3 antibody IIIA4 caused cytoskeletal collapse, reducing adhesion and cell viability in vitro, and prolonged treatment of mice bearing tumours resulted in disruption of the tumour stroma and decreased tumour growth." (PMID 37760615, 2023). "The tumor weight and size were strongly arrested upon EphA3 silence." (PMID 36578556, 2022). "It is concluded that ADAM10-mediated ephrin-A5 shedding promotes PCa metastasis via transforming the role of EphA3 from ligand-dependent tumor suppressor to ligand-independent promoter, and ephrin-A5 in the blood can be used as a new biomarker for PCa metastasis." (PMID 35551177, 2022). "In addition, the pro-tumor function of EphA3 was reversed by the treatment with the exogenous ephrin-A5-Fc, which increased the phosphorylation level of EphA3 in PC-3 (ephrin-A5 ± ) cells." (PMID 35551177, 2022). "Additionally, studies have shown that the ephrin type-A receptor 3 (EphA3) is a tumor-specific therapeutic target and is widely accepted in GBM treatment." (PMID 36059989, 2022). "EPHA3 is a member of the Eph receptor tyrosine kinases and can bind cell membrane ligands to mediate cell communication regulate biological function, including tumour growth, angiogenesis and metastasis." (PMID 36505846, 2022). "Finally, a combined expression of EphA2, EphA3, EphB2 and IL-13RA2 is observed in almost every GB patient, presenting in tumor-infiltrating cells, tumor-initiating cells or GSCs and neovasculature." (PMID 34209513, 2021). "Similarly, anti-EphA3 bound nanoparticles loaded with the DNA alkylation agent temozolomide showed tumor targeting, enhanced tumor cell death and increased survival in a rat glioma model." (PMID 32397088, 2020). "However, subsequent generation of a bsAb against EphA2 and EphA3 showed that even unconjugated antibody was effective in reducing stem cell clonogenicity in vitro, and tumor burden of recurrent GBM xenografts in vivo." (PMID 32397088, 2020). "Positive staining of the AR protein was found in the nucleus, EphA3 was located in the nucleus and cytoplasm of the PCa tissues, and the adjacent normal prostate tissues all showed faint staining according to the IHC of successive tumor tissue sections." (PMID 30958616, 2019).
tumor (continued). "A previous study found that Ad-TERTp-E1A-1504 has no harmful effects on normal cells but inhibits and kills TERT- and EphA3-positive tumor cells, which is mediated through the protein kinase B/mammalian target of rapamycin (AKT/mTOR) signaling pathway via autophagy induction." (PMID 31262977, 2019). "This could be overcome through the use of bi-specific targeting strategies with tumour-specific antigens, such as EphA3." (PMID 31463571, 2019). "In seeking to understand the escape from the initial response, it was notable that ADC therapy also significantly reduced EphA3 receptor levels in recurrent tumours, indicating that escape might be partly mediated by down-regulation of EphA3." (PMID 30562956, 2018). "A 3-h treatment with EphB2-Fc or EphB4-Fc, but not with EphrinB1-Fc or EphrinB2-Fc, produces roundness and decreased size of Stro-1+ BM-MSC, and EphA3+ CD29+ Sca-1hi MSC isolated from tumor niche respond to an EphA3-activating monoclonal antibody (mAb) by fast contraction and apoptosis." (PMID 29941036, 2018). "Alternatively, this finding could indicate that therapy was specifically targeting the EphA3 positive tumour compartment, reducing overall receptor levels." (PMID 30562956, 2018). "Moreover, EphA3 has been shown to be over-expressed and functional on mesenchymal stromal cells in a number of human cancers, and EphA3 antibody targeting inhibited tumour growth by disrupting newly formed tumour microvasculature." (PMID 30562956, 2018). "Although the exact mechanism of how EphA3 regulates its downstream is not well understood, it is hypothesized that EphA subgroup stimulates tumor progression by activating Jak/Stat and Akt/PI3 K signals." (PMID 28465671, 2017). "Moreover, both tumor growth and angiogenesis were inhibited in vivo using soluble EphA2-Fc and EphA3-Fc constructs." (PMID 28415715, 2017). "However, in a series of studies of non-small cell lung cancer (NSCLC), EPHA3 was identified as a tumor suppressor with decreased expression levels." (PMID 27101199, 2016). "The results suggest that the expression of EphA3, EphA2, eA1, and eA5 in cells in culture differ from their expression in tumor specimens pointing to an elevated and more frequent expression of the receptors in cells than tumors and the opposite true for the ligands." (PMID 27494882, 2016). "In addition, EphA3 is present in GBM tumor-initiating cells, with a prominent effect on their biological behavior, as demonstrated by others." (PMID 27494882, 2016). "Our data suggests that EPHA3 plays a tumor suppressor role and may be a candidate target for developing therapeutic strategies to overcome drug resistance in SCLC." (PMID 27101199, 2016). "However, in a highly cystic GBM sample (BTCOE4843), EphA3 was present in a tumor lysate, but barely detectable in tumor-derived cells." (PMID 27494882, 2016). "The anti-tumor efficacy of Ad-TERTp-E1A- EphA3 shRNA was further validated in vivo." (PMID 26980708, 2016). "We found that CD68 and EphA3 co-stain in a GBM tumor microenvironment indeed." (PMID 27494882, 2016). "They found that Ad-TERTp-E1A-EphA3 shRNA had 3.5- and 1,400- fold greater ability to kill EphA3 and TERT expressing tumor cells compared to Ad-TERTp-E1A-NC and Ad-ΔE1A-EphA3 shRNA, respectively, while had little effect on cells that modestly expressed EphA3 and TERT." (PMID 26980708, 2016). "Thus, Ad- TERTp-E1A-1504 does not harm normal cells but has dual inhibiting and killing effects on TERT- and EphA3-positive tumor cells, and this effect is mediated by the AKT/mTOR signaling pathway via induction of autophagy." (PMID 25978371, 2015). "Tumor burden analysis at 19 weeks after CMV-AdCre infection showed that constitutive loss of EphA3 did not alter mutant Kras-driven lung ADC progression." (PMID 25713296, 2015).
tumor (continued). "EphA3 cancer somatic mutations are distributed throughout the domains of the receptor and some have been shown to impair ephrin ligand-dependent receptor signaling, suggesting a tumor suppressor role for the EphA3/ephrin interaction, which has been substantiated by functional studies." (PMID 25993310, 2015). "In addition, EphA3 has been reported to be widely upregulated in the tumor stroma and in some types of cancer cells." (PMID 25993310, 2015). "While further functional characterization of EphA3 in MSCs during adult neovascularisation is ongoing, our parallel studies in solid tumour progression indicate notable EphA3 expression and function also in the vascularised tumour microenvironment of solid and haematopoietic tumours." (PMID 25420155, 2014). "Notably, EphA3 is implicated and recognised as an anti-cancer target in solid and hematopoietic tumors, and we recently discovered EphA3 overexpression and function on bone marrow-derived MSCs that are recruited into the vascularised tumour microenvironment." (PMID 25420155, 2014). "In contrast, EPHA3 and MITF are under-expressed in cancers or have been shown to act as tumor suppressors; the somatic mutations may create new target sites that lead to increased inhibition of translation or degradation of the mRNAs." (PMID 23091610, 2012). "For EPHA3 we found clear evidence in the literature that it acts as a tumor suppressor." (PMID 21575214, 2011). "In addition, the role of A-class Eph receptors was analyzed and inhibition of tumor angiogenesis and suppressed tumor growth in vivo was demonstrated for soluble EphA2-Fc and EphA3-Fc receptors." (PMID 20224755, 2010). "Soluble EphA2-Fc or EphA3-Fc receptors inhibit angiogenesis and tumor formation in multiple models." (PMID 15563374, 2004). "Further studies have shown that soluble EphA2-Fc and EphA3-Fc receptor constructs inhibit tumour angiogenesis and growth in vivo, providing the first functional evidence for EphA receptor regulation of tumour angiogenesis." (PMID 12865906, 2003). "Previous studies have also implicated EPHA3 in angiogenesis and invasive pathways in various cancers, further supporting the hypothesis that HOC-mediated suppression of EPHA3 contributes to reduced tumor recurrence and aggressiveness observed in this study model." (PMID 41514539, 2025). "Studies on EphA3 also suggested that this protein may act as a tumor suppressor in ESCC." (PMID 39839790, 2024). "Finally, we sought to characterise EphA3 expression in the TME of human tumours." (PMID 37760615, 2023). "Taken together, these findings indicate that interaction of IL-26 and EphA3 induces increased phosphorylation of AKT and JNK not only in murine TNBC but also in human TNBC, hence activating the EGFR-TKI-associated bypass pathway to result subsequently in tumor growth." (PMID 34021125, 2021). "In addition, PET/CT imaging could be used to screen EphA3 levels in patient tumours prior to commencing Ifabotuzumab therapy." (PMID 30562956, 2018). "Alternatively, EPHA3 mutations may affect the tumor phenotype in aspects not directly investigated in this study, such as angiogenesis, the immune response of the host or growth under starvation/hypoxic conditions." (PMID 28169277, 2017). "Alternatively, EPHA3 levels could be associated with tumor stage, as suggested by Xi and Zhao31, but have no prognostic value when the analysis is restricted to patients with the same disease stage." (PMID 28169277, 2017). "Furthermore, higher expression levels of EPHA3 in SCLC tumor samples were correlated with longer overall survival of patients, implying that EPHA3 might be associated with chemosensitivity." (PMID 27101199, 2016).
tumor (continued). "Finally, the gene-set #2 also contained several tumour suppressors (EPHA3 and EPHB2) and proto-oncogenes (AKT1, AURKA, ETV6, MITF and PIK3CA), which expands on the observed enrichment of the immune response and suggests that this gene-set has a critical role in breast tumorigenesis." (PMID 19826428, 2009). "By contrast, module 2 and 3, which were only downregulated in EGF-stimulated SHP2WT cells, contained several tumor suppressors, such as NRG1, MAP3K1, CAVIN3, EPHA3/7, CTNNA1/3, and NOTCH3." (PMID 40631144, 2025). "EphA3 was identified to be widely expressed in the stroma of diverse cancer types, present on MSCs and specific CAF subtypes in human and mouse tumours." (PMID 39780187, 2025). "EphA3 is detected in up to 60% of GBM samples and is particularly enriched in invasive fronts, perivascular niches, and tumor-infiltrating immune cells." (PMID 41200151, 2025). "It was thus possible to identify genes (CNTN1, FAT3, EPHA3, EPHA5, NLGN1, etc.)that contribute to PC2 and are differentially expressed in radial glial cells between normal and tumor samples." (PMID 38609519, 2024). "Overall, we revealed that the tumor-suppressive function of VIM-AS1 was regulated by cg02746869, which modulated EPHA3 mRNA stability, suggesting a basis for HCC progression and the development of potential biomarkers and therapeutic targets for HCC." (PMID 39617786, 2024). "Our results thus indicate expression of the cell guidance receptor EphA3 in distinct CAF subpopulations is important in supporting tumour angiogenesis and tumour growth, highlighting its potential as a therapeutic target." (PMID 37760615, 2023). "METTL14 performed tumor suppressor functions similar to that of METTL3 in the development of GSCs by targeting mRNA levels of ADAM19, EPHA3 and KLF4." (PMID 34521394, 2021). "In the current study, exogenous IL-26 induced dephosphorylation of EphA3 in TNBC, followed by phosphorylation of AKT and JNK leading to suppression of ER stress signaling, resulting in enhanced tumor growth of EGFR-TKI-resistant TNBC." (PMID 34021125, 2021). "Our study revealed that interaction of IL-26 and EphA3 in TNBC activates AKT and JNK, leading to tumor proliferation by inhibiting EGFR-TKI-provoked PERK-eIF2α-DDIT3 pathway and ER stress-associated cell death." (PMID 34021125, 2021). "IL-26 induced dephosphorylation and downmodulation of EphA3 in TNBC, which resulted in increased phosphorylation of AKT and JNK against EGFR-TKI-induced endoplasmic reticulum (ER) stress, leading to tumor growth." (PMID 34021125, 2021). "Overexpression of EphA3 has also been reported in glioblastoma and this resulted in inhibition of the MAPK pathway, keeping tumour cells in a dedifferentiated and tumorigenic state." (PMID 33430066, 2021). "Taken together, our data suggests that αDG, along with EphA3, are critical components of this MES-like tumour state, promoting functional interaction with BM proteins likely within the TME and perivascular niche." (PMID 31463571, 2019). "Our findings indicate that αDG is functionally glycosylated and cooperates with EphA3 and integrin α6 receptors to mediate an MES-like state and further acts to anchor GSCs residing in perivascular tumour regions." (PMID 31463571, 2019). "To assess IIIA4 brain penetration and tumour uptake, we engrafted the EphA3-positive U251 cell line into the right striatum of a NOD/SCID mouse and allowed the tumour to form orthotopically for 30 days." (PMID 30562956, 2018). "Our results shed light on further clinical evaluation of EphA3 targeting in GBM, and highlight this receptor as a tumour-specific candidate suitable for ADC or RIT strategies." (PMID 30562956, 2018). "EPHA3 expression was detectable in 18 of 25 (72 %) normal lung tissue samples, compared with 21 of 61 (34.4 %) SCLC tumor samples (*P < 0.05, χ2 test)." (PMID 27101199, 2016).
tumor (continued). "To explore the possible role of EPHA3 in MDR, we assessed the influence of EPHA3 on chemoresistance, cell cycle, apoptosis, and tumor growth, as well as the relationship between EPHA3 and the expression of PI3K, BMX, and STAT3 in SCLC." (PMID 27101199, 2016). "Having established that EphA3 and EphA2 together are promising molecular targets in GBM tumor cells, tumor neovasculature (EphA2), tumor-initiating and tumor-infiltrating cells of monocytic origin, we focused on combinatorial targeting of these receptors." (PMID 27494882, 2016). "Western blot confirmed that Ad-TERTp-E1A-1504 and Ad-ΔE1-1504 significantly suppressed EphA3 and AKT, mTOR and 4-ebp1 phosphorylation compared with Ad-TERTp-E1A-NC and Ad-ΔE1-NC, respectively, in TERT- and EphA3-positive tumor cells." (PMID 25978371, 2015). "In ERMS, high expression of PAX7 upregulates EPHA3 and EFNA1 to promote migration and invasiveness of tumor cells." (PMID 26636678, 2015). "Cell viability assays and ED50 studies of growth inhibition confirmed that Ad-TERTp-E1A-1504 has 3.5- and 1,400-fold greater ability to kill EphA3- and TERT-expressing tumor cells compared to Ad-TERTp-E1A-NC and Ad-ΔE1A-1504, respectively." (PMID 25978371, 2015). "We further confirmed a significant decrease in tumour growth over a longer timeframe in doxycycline-treated compared to untreated EphA3 shRNA mice, to rule out possible variation in transgenic mouse strains." (PMID 37760615, 2023). "Analysis of early-stage tumours showed EphA3 was almost exclusively expressed in GFP+, CD90+/Sca1-high MSCs, and this population was significantly reduced in tumours from EphA3 shRNA host mice compared to control hosts, suggesting reduced recruitment from the bone marrow." (PMID 37760615, 2023). "We determined previously that EphA3 was frequently expressed in the stroma in a range of different human tumours, and in tumour cell xenografts in mice, even when not expressed in the tumour cells." (PMID 37760615, 2023). "We previously found that EphA3, known to be overexpressed in haematopoietic malignancies and many solid tumour types, is most commonly expressed in the tumour microenvironment in human tumour samples, but not in normal tissues." (PMID 37760615, 2023). "As we previously detected elevated EphA3 expression in bone marrow-derived MSCs in human tumour xenograft models, we analysed bone marrow cells from EphA3 and control shRNA hosts bearing LLC tumours." (PMID 37760615, 2023). "Thus, we set out to better define the expression and function of EphA3 in the TME, and to determine its requirement for supporting tumour development, using syngeneic tumours in transgenic mice with inducible shRNA-mediated knockdown of EphA3 expression." (PMID 37760615, 2023). "Once again, EphA3 knockdown in mice significantly inhibited tumour growth compared to control knockdown mice, also indicating a role for EphA3 in the TME of tumours in which EphA3 is expressed in tumour cells." (PMID 37760615, 2023). "Noteworthy, our findings suggest that EphA3 may be considered as a novel RAGE target gene facilitating BC invasion and scattering from the primary tumor mass." (PMID 37434266, 2023). "A CSRS scoring system including four CS genes (MYC, DLX2, EPHA3, and LIMK1) was constructed, which could distinguish the survival outcome, tumor microenvironment (TME) status, and ICB treatment response of patients with different CSRS score." (PMID 36106335, 2022). "The absence of ephrin-A5 activates EphA3 signaling via ligand-independent pathways that promotes tumor progression." (PMID 35551177, 2022). "EphA3, an essential regulatory target of ADAM10 through cleaving its primary ligand ephrin-A5, is a member of the receptor tyrosine kinase family, and has been reported to have dual biological effects in tumor progression." (PMID 35551177, 2022).